THSD7A (thrombospondin type 1 domain containing 7A)
Diseases named in the same sentence as THSD7A in open-access papers (continued):
Sharing a sentence is not in itself a finding about the gene and the disease.
tumor (28 papers, 2017 to 2025). "In recent years, multiple studies have reported that THSD7A-positive malignancy-associated MN patients are positive for THSD7A staining in both renal and tumor tissues." (PMID 38686366, 2024). "THSD7A positivity was associated with advanced tumor stage (p < 0.001), positive nodal status (p < 0.001) and with a high Gleason score (p < 0.001)." (PMID 36673031, 2023). "The association between neoplasm and MN is probably the result of the expression of THSD7A antigens within the tissues of some tumors." (PMID 35564696, 2022). "Tumor growth requires an increased intratumoral blood supply that promotes angiogenesis, in which THSD7A, a tumor-associated antigen, is overexpressed, allowing regional exposure of the autoantigen to the immune system." (PMID 34337081, 2021). "Simultaneous positivity for THSD7A in renal and tumor tissue suggests that THSD7A may play an important role in pathogenic mechanism leading to MN associated with tumors." (PMID 38686366, 2024). "This study found that the expression of THSD7A may be associated with the suppression of the anti-tumor immune response." (PMID 37905960, 2023). "Extrinsic protein overexpression as a trigger for antigenicity is also suggested by malignancy-associated THSD7A-positive MN in which THSD7A is abnormally expressed in tumor tissue due to polysomy of chromosome 7, providing a potential source of antigen that can overwhelm host tolerance mechanisms." (PMID 34899763, 2021). "Therefore, during tumor development, upregulation of THSD7A and persistent expression of pathogenic epitopes triggers an immune response." (PMID 34337081, 2021). "Therefore, it is speculated that THSD7A may play a role in the pathogenesis of tumor-associated MN through T cells." (PMID 38686366, 2024). "Two years later, the patient was diagnosed with bladder cancer, and THSD7A staining was also positive in the tumor tissue." (PMID 38686366, 2024). "Larger studies focusing on neoplasms identified THSD7A expression in a wide variety of neoplasms, raising questions about how well immunohistochemically-detected tumor antigen expression will associate with development of MN in an individual patient." (PMID 38596642, 2024). "Similar to THSD7A, the association between NELL1 MN and malignancy is made further intriguing by the presence of tumor staining in reported cases, usually of solid tumors like breast or prostate cancer for NELL1." (PMID 38596642, 2024). "In patients with tumors such as rectal cancer, NF1-related neurofibromas and endometrial cancer combined with MN, THSD7A was also found to be positive in the kidney and tumor tissue." (PMID 38686366, 2024). "THSD7A promotes angiogenesis, which is closely associated with the tumor microenvironment, growth, and metastasis in NSCLC, and tumor-associated angiogenesis promotes tumor progression and metastasis (59, –, 61)." (PMID 37074188, 2023). "Next, we evaluated the efficacy of THSD7A expression in predicting the half-maximal inhibitory concentration (IC50) values of anti-tumor drugs and checkpoint expression." (PMID 37905960, 2023). "We explored the relationship between THSD7A expression and sensitivity of anti-tumor drugs and immune checkpoint levels." (PMID 37905960, 2023). "An example is a Japanese analysis where eight patients with MN related to anti-THSD7A developed a tumor within three months of the study." (PMID 35564696, 2022). "Studies have shown that the THSD7A acts via the TGF-β (common in non-tumor diseases) or mTOR signaling pathways (common in tumor diseases)." (PMID 36506585, 2022). "The analysis of data from the literature shows a relationship between the THSD7A antigens and their antibodies with neoplasm, while this link has been weak with PLA2R antigen and anti-PLA2R antibodies." (PMID 35564696, 2022). "All of this gives MN related to THSD7A a character of a specific type of paraneoplastic syndrome or, more rarely, make it a revelator of neoplastic disease." (PMID 35564696, 2022).
tumor (continued). "In a subsequent systematic analysis of THSD7A expression in malignant tissues, the protein was found to be expressed in many neoplasias." (PMID 33825066, 2021). "THSD7A affects kidney function; its presence in SigIQGAP1NW is consistent with our observed THSD7A downregulation in ccRCC (n = 523) compared to non-tumor kidney tissues (n = 100)." (PMID 33266355, 2020). "THSD7A protein was also detected in follicular dendritic cells in the light zone of the germinal center of the tumor–infiltrated lymph nodes." (PMID 29623759, 2018). "Immunohistochemical evaluation of the tumor tissue found an increase in THSD7A protein expression, indicating that the tumor was actively synthesizing THSD7A." (PMID 29623759, 2018). "In other words, the later Clinical stage and the higher degree of tumor differentiation were, the higher expressing quantity of Thsd7a would be." (PMID 28947992, 2017). "For that reason, we investigated the role of THSD7A as a potential tumor marker in LSCC and whether THSD7A expression has an impact on the expression level of FAK." (PMID 37445817, 2023). "In addition to that, other groups report on THSD7A expression in different tumor types and a possible relationship between malignant diseases and MN." (PMID 37445817, 2023). "Several studies indicate that THSD7A might at least play a role in the prognosis of different tumor types and that it possibly activates FAK-dependent signaling pathways." (PMID 37445817, 2023). "Less than 5% of non-tumor prostate tissue revealed very weak cytoplasmic THSD7A expression." (PMID 36673031, 2023). "Several studies indicate that THSD7A might play a role at least in the prognosis of different tumor types." (PMID 36673031, 2023). "Based on these data, we speculate that the downregulation of THSD7A in GBM tumor cells affects microvascular formation in GBM." (PMID 32253832, 2020). "THSD7A expression was detected by immunohistochemical staining in tumor tissues." (PMID 31443644, 2019). "And all with proteinuria were patients with tumor tissue THSD7A positive." (PMID 31443644, 2019). "Finally, it was uncovered by microarray analysis that a variety of tumor genes and pathways related to Thsd7a." (PMID 28947992, 2017). "In addition to our previous results, several other reports indicate that THSD7A might play a role in different tumor types." (PMID 36673031, 2023). "Furthermore, several studies indicate that THSD7A might at least play a role in the prognosis of different tumor types." (PMID 37445817, 2023). "Moreover, THSD7A was also present in follicular dendritic cells of tumor-infiltrated lymph nodes." (PMID 33825066, 2021). "THSD7A-positive MN is not strongly associated with underlying autoimmune diseases (such as systemic lupus erythematosus) but is seen in some patients with malignancy, where there is corresponding increased expression in tumor tissue." (PMID 34899763, 2021). "This may be one of the ways for THSD7A to establish the relationship between tumor and IMN." (PMID 33042109, 2020). "After investigating the role of THSD7A as a new potential tumor antigen by evaluating over 20,000 tissue spots in more than 70 different tumor entities by immunohistochemistry using tissue microarrays, the study found that THSD7A expression was highly variable in different neoplasia." (PMID 29623759, 2018). "In addition, THSD7A protein was also found in the tumor tissue." (PMID 29623759, 2018). "Through a large number of high-quality research, we discuss the similarities between PLA2R and THSD7A, focus on the effect of PM2.5 and tumor in MN, and allow to better identify the potential pathogenic factors in MN." (PMID 34337081, 2021). "When the kidney disease was alleviated, the patient’s serum THSD7A antibody turned negative, and the patient’s tumor was also under control." (PMID 38686366, 2024).
tumor (continued). "Assuming that the amplification of FGFR1 might describe a specific manner of tumor development in LSCC, it is likely that THSD7A positivity describes a different manner of tumor development." (PMID 37445817, 2023). "However, it has been reported that THSD7A-positive MN and NELL-1-positive MN occur under the action of tumor, drugs and other secondary factors." (PMID 38250076, 2023). "AQP1 is involved in tumor malignancy by facilitating the migration and invasion of GBM cells, and promoting the formation of vascular beds that are characteristic of GBM by downregulating THSD7A." (PMID 32253832, 2020). "Non-tumor tissue of the lung was mainly negative for THSD7A." (PMID 37445817, 2023). "Tumour tissues from cases with malignancy (case 13 and 14) were negative for THSD7A (not shown)." (PMID 30868298, 2019). "Moreover, the same to the previous studies, Thsd7a had been confirmed that it was significantly related with ERK/MAPK signaling, which promotes the role of intermediary and amplified signal in the process of tumor invasion and metastasis." (PMID 28947992, 2017). "And authors suggested that Thsd7a might have a function as tumor suppressor gene, which was likely to facilitate the progress of tumor growth without it." (PMID 28947992, 2017). "In this instance, IF results for IgG4, PLA2R, and THSD7A in the kidneys were negative, indicating a predilection for SMN and the potential for a tumor." (PMID 39009965, 2024). "We found that AQP1 was expressed by GBM tumor cells, but these AQP1‐positive tumor cells did not co‐express THSD7A." (PMID 32253832, 2020). "Secondly, considering the differences of human (minority: Kazakh, vivo) and cell line (Eca 109 and EC 9706, vitro), tumor (this study) and non-tumor (other researches), there might be some biased results, which need a large panel of ESCC patients and cell lines with the endogenous amount of Thsd7a." (PMID 28947992, 2017).
kidney disease (9 papers, 2016 to 2025). "Based on previous studies of PLA2R-positive MN and THSD7A-positive MN, it is known that the titer of serum antibodies is closely related to the clinical severity and disease change of patients with kidney disease." (PMID 38250076, 2023). "However, after 1 year, upon the reoccurrence of the kidney disease, the THSD7A staining was positive." (PMID 38686366, 2024).
benign tumors (1 paper, 2021). "In addition, several studies found that anti-THSD7A antibodies were correlated with malignancy, benign tumors, and neurological disease, which increases the possibility of extrarenal anti-THSD7A immunization." (PMID 34337081, 2021).
cardiac disease (1 paper, 2022). "Combined with the genome-wide association study (GWAS) analysis, cardiac disease-associated genes Rasd1, Thsd7a, Ednra, and Tns1 were identified." (PMID 35938163, 2022).
cardiovascular disease (1 paper, 2021). "The present study offers supportive evidence for THSD7A and RMST candidacy in cardiovascular disease." (PMID 34140969, 2021).
THSD7A also shares sentences with these, for which no sentence is quoted: gallbladder carcinoma (4 papers); esophageal cancer (2); infection (2); lupus (2); renal carcinoma (2); acute tubular necrosis (1); adenocarcinoma (1); bladder cancer (1); cervical cancer (1); chronic inflammatory demyelinating polyneuropathy (1); endometrial cancer (1); Glomerular sclerosis (1); glomerulopathy (1); head and neck cancer (1); Hematuria (1); Hypercholesterolemia (1); hypercoagulable (1); hypereosinophilic disorders (1); hyperlipidemia (1); IgA vasculitis (1); major depression disorder (1); mixed adenoneuroendocrine carcinoma of (1); neurological disease (1); non-small cell lung carcinoma (1); pharynx cancer (1); renal cell carcinoma (1); Sjögren's syndrome (1); stomach adenocarcinomas (1); ZIKV infection (1).